NDUFS4 (NADH:ubiquinone oxidoreductase subunit S4)
Diseases named in the same sentence as NDUFS4 in open-access papers (continued):
Sharing a sentence is not in itself a finding about the gene and the disease.
Alzheimer disease (4 papers, 2021 to 2023). A progressive, neurodegenerative disease characterized by loss of function and death of nerve cells in several areas of the brain leading to loss of cognitive function such as memory and language. "This “Alzheimer’s disease” pathway overlaps with other AV-1451-associated pathways that relate to mitochondrial respiration, electron transport, and oxidative phosphorylation (NDUFS4 & 8, NDUFA6 &7, UQCRQ, & COX17), as well as metabolism (NDUFS4 & 8, NDUFA6 &7, UQCRQ, COX17, & ETHE1)." (PMID 35774552, 2022). "Among the top-ranked proteins in the PMbrown network, Ndufs4 and Slc25a5 are involved in Alzheimer’s disease pathway, showing that they play an important role in neurodegenerative diseases resulting from sleep disorders." (PMID 35432311, 2022). "The nominal “Alzheimer’s disease” pathway is the foremost one identified by BioPlanet for the discriminant gene set for FDG-18, implicated via the influence of BACE2 and NDUFS4." (PMID 35774552, 2022). "Of the three AD pathologies probed by PET imaging, Tau deposition (by AV-1451) appears to reveal the most relevant pathways related to AD, as well as including “Alzheimer’s disease” itself as the most highly significant BioPlanet-identified pathway via NDUFS4 & 8, NDUFA6 & 7 and UQCRQ." (PMID 35774552, 2022).
lactic acidosis (4 papers, 2016 to 2023). Metabolic acidosis characterized by the accumulation of lactate in the body. "As previously reported, Ndufs4−/− mice had lower blood pH associated with lactic acidosis, compared with control mice." (PMID 30520688, 2019). "Administration of NAD+ precursor, nicotinamide mononucleotide (NMN) extended lifespan of Ndufs4-KO mice and attenuated lactic acidosis." (PMID 30816177, 2019). "NMN treatment suppressed serum lactic acidosis in Ndufs4-KO mice, suggesting an improvement of systemic metabolism by the treatment." (PMID 30816177, 2019). "Lactic acidosis is a common symptom in LS and upregulation for glycolysis has been reported for the Ndufs4(KO)." (PMID 26824698, 2016).
Leber hereditary optic neuropathy (4 papers, 2020 to 2024). Leber's hereditary optic neuropathy (LHON) is a mitochondrial neurodegenerative disease affecting the optic nerve and often characterized by sudden vision loss in young adult carriers. "Moreover, they tested the effects of genetic inactivation of miR-181a and b in a chemical (rotenone-induced) and genetic (Ndufs4-/-) murine models of Leber hereditary optic neuropathy (LHON, MIM535000), a mitochondrial disorder characterized by degeneration of RGCs and loss of central vision." (PMID 32197476, 2020). "Although transgenic mice lacking the mitochondrial complex I accessory subunit NDUFS4 develop early-onset optic atrophy, severe systemic mitochondrial dysfunction leads to very early death and makes this mouse line impractical for studying the pathobiology of mitochondrial optic neuropathies." (PMID 33004958, 2020).
depression (3 papers, 2020 to 2026). "At P50, 0.2% caused significant respiratory depression in Ndufs4(−/−) mice, with increasing effect in repeat exposures." (PMID 37770252, 2023). "To test the hypothesis that suboptimal mitochondrial function increases susceptibility to stress-related psychopathologies, such as depression, we used a novel mouse model with a partial deficiency of mitochondrial complex I function due to lower NDUFS4 protein abundance (Ndufs4GT/GT mice)." (PMID 32488052, 2020). "By prioritizing UCP2, SOD1, HK2, NDUFS4, and NEU1, our findings highlight novel, immune-mediated pathways in depression and nominate promising targets for future diagnosis and therapeutic intervention." (PMID 41601681, 2026).
Gliosis (3 papers, 2014 to 2024). Gliosis is the focal proliferation of glial cells in the central nervous system. "Apart from the differences observed in survival and clasping onset, female GFAP-IL6/Ndufs4 KO mice were phenotypically similar to males in terms of disease progression and gliosis." (PMID 38212783, 2024). "Gliosis is a feature of LS, and was also observed in Ndufs4 KO mice." (PMID 25312000, 2014).
melanoma (3 papers, 2020 to 2025). A malignant, usually aggressive tumor composed of atypical, neoplastic melanocytes. "Consistent with facts that NDUFS4 mediated oxidative metabolism acts as a barrier to the response of PD-1 blockade in melanoma, and more and more studies convey the concept that tumor cell metabolites epigenetically regulate the immune cell phenotype." (PMID 37469574, 2023). "A 2025 Nature Cancer study demonstrated that deletion of NDUFS4 in mouse models of melanoma and BC increased mitochondrial acetyl-CoA production, enhanced MHC-I antigen presentation, and sensitized tumors to T-cell-mediated cytotoxicity and checkpoint blockade." (PMID 41157129, 2025). "Studies have shown that down-regulation of NDUFS4 can result in a significant down-regulation of mitochondrial complex I activity and can block the binding of cytosol to membrane-bound proteins, thereby inhibiting the migration potential of melanoma cells." (PMID 33101026, 2020). "In the view of drug targets, NDUFS4 or NDUFS7 is reported as the targeted gene by casticin or nebivolol for its role in inhibiting cell migration and invasion in mouse melanoma B16F10 cells, or in blocking complex I activity related colon and breast tumor growth, respectively." (PMID 37469574, 2023).
mitochondrial encephalomyopathy (3 papers, 2017 to 2023). A heterogenous group of disorders characterized by alterations of mitochondrial metabolism that result in muscle and nervous system dysfunction. "Here we used an adeno-associated virus (AAV) vector to deliver human NDUFS4 (hNDUFS4) in Ndufs4−/− mice and test proof-of-principle feasibility and efficacy of a gene therapy strategy aimed to ameliorate the clinical and biochemical phenotype of an otherwise fatal mitochondrial encephalomyopathy." (PMID 28753212, 2017).
osteopetrosis (3 papers, 2016 to 2023). Osteopetrosis, also known as marble bone disease, is a descriptive term that refers to a group of rare, heritable disorders of the skeleton characterized by increased bone density on radiographs. "Interestingly, mice with global CI subunit Ndufs4 knock-out have systemic inflammation and osteopetrosis due to shift in macrophage polarization and osteoclast differentiation." (PMID 28424480, 2017).
anemia (2 papers, 2023). A reduction in the number of red blood cells, the amount of hemoglobin, and/or the volume of packed red blood cells. "As expected, Ndufs4−/− mice fed a low iron diet showed signs of microcytic, hypochromic anemia consistent with iron deficiency." (PMID 36799301, 2023). "Iron restriction in Ndufs4−/− mice downregulated FTH1 expression, consistent with iron deficiency anemia." (PMID 36799301, 2023).
Arrhythmia (2 papers, 2022 to 2023). Any cardiac rhythm other than the normal sinus rhythm. "Approximately 2–3 months after tamoxifen‐induced deletion of Ndufs4, 87.5% of the HCN4–Ndufs4−/− mice developed various forms of arrhythmia, including atrial or ventricular premature contractions, sinus bradycardia and frequent sinus pauses resembling those found in germline Ndufs4−/− LS mice." (PMID 35872650, 2022).
Bradycardia (2 papers, 2022 to 2023). A slower than normal heart rate (in adults, slower than 60 beats per minute). "In this study, we show evidence of the direct mechanistic role of mitochondrial oxidative stress in bradycardia using mitochondrial disease LS mice, which were generated from a germline homozygous deletion of exon 2 of the encoding gene Ndufs4 (Ndufs4−/−)." (PMID 37237867, 2023). "We performed electrocardiograms (ECGs) from conscious immobilized Ndufs4−/− mice to understand the characteristics of bradycardia." (PMID 37237867, 2023). "The spectrum of bradyarrhythmia in Ndufs4−/− mice includes frequent sinus node dysfunction (SND), such as sinus pauses and sinus bradycardia; episodic atrioventricular (AV) conduction block that manifested as Mobitz type II second-degree AV block; or rarely, a high-grade AV block." (PMID 37237867, 2023).
breast carcinoma (2 papers, 2024 to 2025). "For example, multiple Complex I subunits, such as NDUFB1, NDUFS4, NUBPL, and NDUFA7, have been implicated in the metabolic plasticity of breast cancer cells." (PMID 41157129, 2025).
cardiac hypertrophy (2 papers, 2023). "NDUFS4, a protein critical for complex-I assembly and loss of which leads to cardiac hypertrophy mapped near the locus but outside the region of linkage disequilibrium." (PMID 37276142, 2023). "Using 100 HMDP inbred strains of mice, here we found that cardiac miR-27b expression was inversely correlated with heart weights and that mature miR-27b-3p appears to have a protective role in reducing cardiac hypertrophy via increasing NDUFS4 protein levels." (PMID 37276142, 2023). "Taken together, we report that natural variation in NDUFS4 protein levels affect other complex I proteins resulting in reduced complex I activity and cardiac hypertrophy." (PMID 37276142, 2023). "In the absence of cardiac hypertrophy, the current germline Ndufs4−/− (LS) mice showed severe sinus node dysfunction and intermittent AV conduction block (reported in ~5% in LS patients)." (PMID 37237867, 2023).
cognitive deficits (2 papers, 2017 to 2022). "NDUFS4 codes for a mitochondrial subunit known to bind oligomeric Aβ and may have a role in the cognitive deficits of AD via oxidative stress." (PMID 35774552, 2022).
diabetes (2 papers, 2023 to 2024). "On the other hand, primary podocytes from diabetic mice overexpressing Ndufs4 show significantly reduced oxidized/reduced mito-roGFP ratios compared with podocytes from diabetic mice, indicating Ndufs4 overexpression prevents enhanced mROS in diabetes." (PMID 38438382, 2024). "Taken together, the consistently reduced expression of Ndufs4 in both murine models of diabetes and in human DKD subjects suggest that Ndufs4 may play an important role in progression of DKD." (PMID 37461606, 2023). "However, it is important to emphasize that our data suggest that the diabetes-induced ETC dysfunction is not exclusively related to NDUFS4 deficiency and the abundance of several other subunits of CI were altered in the podocytes of diabetic mice." (PMID 37461606, 2023).
diabetic kidney disease (2 papers, 2023 to 2024). Progressive kidney disorder caused by vascular damage to the glomerular capillaries, in patients with diabetes mellitus. "Here, we generated diabetic mice with podocyte-specific overexpression of Ndufs4, an accessory subunit of mitochondrial complex I, as a model to investigate the role of ETC integrity in diabetic kidney disease (DKD)." (PMID 37461606, 2023). "Here, we generate diabetic mice with podocyte-specific overexpression of Ndufs4, an accessory subunit of mitochondrial complex I, as a model investigate the role of ETC integrity in diabetic kidney disease (DKD)." (PMID 38438382, 2024).
epilepsy (2 papers, 2024 to 2025). A brain disorder characterized by episodes of abnormally increased neuronal discharge resulting in transient episodes of sensory or motor neurological dysfunction, or psychic dysfunction. "Fos gene product staining studies in Ndufs4-cKO mice have revealed neuronal activation in the cortex, dentate gyrus of the hippocampal formation, and the amygdala, among other areas associated with epilepsy in humans and rodents." (PMID 41321311, 2025). "Based on our results, we propose that the loss of LHX6 neurons in the GPe leads to reduced inhibitory control in the STN, contributing to the propagation of epilepsy in Ndufs4-cKO mice." (PMID 41321311, 2025). "The appearance of seizures in Ndufs4 KO mice have been previously observed, and there is a significant correlation between inflammation and epilepsy, as seizures can trigger inflammation or inflammation can exacerbate the severity of seizures." (PMID 38212783, 2024). "Thus, our results suggest that the inhibitory network of basal ganglia is compromised in Ndufs4-cKO mice, impairing the control of excitatory neuron activity and leading to the development of epilepsy." (PMID 41321311, 2025). "Therefore, it cannot be ruled out that the sex-dependent effect on survival in GFAP-IL6/Ndufs4 KO mice is due to a greater susceptibility to developing epilepsy, or a greater severity of seizures in GFAP-IL6/Ndufs4 KO female mice compared to GFAP-IL6/Ndufs4 KO male mice and Ndufs4 KO mice." (PMID 38212783, 2024). "This suggests that Ndufs4 deletion limited to the GPe (and TRN) is not sufficient to trigger epilepsy or convulsive events." (PMID 41321311, 2025).
mitochondrial Leigh syndrome (2 papers, 2020 to 2025). "To note, differences between nerve cells and peripheral cells have been reported in a metabolic study comparing primary neurons, astrocytes, and fibroblasts cultures deficient for the mitochondrial complex I subunit NDUFS4, a model for the mitochondrial Leigh syndrome, a severe neurological disease." (PMID 33551720, 2020). "We have previously demonstrated that chronic inhaled hypoxia is remarkably therapeutic in the premier animal model of mitochondrial Leigh syndrome, the Ndufs4 knockout (KO) mouse." (PMID 39965572, 2025).
neuropathy (2 papers, 2020 to 2024). A disorder affecting the nervous system that manifests with pain, tingling, numbness, and/or muscle weakness. "We conducted metabolomic analysis using the brains of Ndufs4 KO mice, a model of CI deficiency that develops a fatal neuropathy and recapitulates human Leigh syndrome." (PMID 32483148, 2020).
Seizure (2 papers, 2024 to 2025). A seizure is an intermittent abnormality of nervous system physiology characterized by a transient occurrence of signs and/or symptoms due to abnormal excessive or synchronous neuronal activity in the brain. "Ndufs4(−/−) performance on a rotarod assay is not significantly impaired at P30, but the rotarod assay at this age can be used to assess exercise-induced seizure incidence." (PMID 38883711, 2024).
adenovirus infection (1 paper, 2023). "The results showed that the adenovirus infection rate was about 90%, and Ndufs4 mRNA and protein were decreased by 76.7% and 64.9%, respectively." (PMID 36741296, 2023).
Anxiety (1 paper, 2017). Intense feelings of nervousness, tension, or panic often arise in response to interpersonal stresses. "The Ndufs4 cKO mice also showed anxiety-like behaviors in the open field, elevated plus maze, light/dark exploration, and social interaction tests." (PMID 28327638, 2017). "Collectively, these data suggest that Ndufs4 cKO mice exhibit age-dependent, anxiety-like behavior." (PMID 28327638, 2017).
autosomal dominant optic atrophy (1 paper, 2022). An autosomal dominant hereditary condition characterized by optic atrophy and progressive visual loss. "These include an Ethe1−/− model of ethylmalonic encephalopathy (EE), a Tymp−/− model of mitochondrial neuro-gastrointestinal encephalo-myopathy (MNGIE), and Nr2f1−/− and OPA1delTTAG models for autosomal dominant optic atrophy (ADOA, BBSOA) as well as an Ndufs4−/− model of Leigh syndrome." (PMID 35203486, 2022).
Cachexia (1 paper, 2022). Severe weight loss, wasting of muscle, loss of appetite, and general debility related to a chronic disease. "As noted, treatment with pexidartinib prevented both cachexia and hypoglycemia in the Ndufs4(KO) mice in a dose-dependent manner, consistent with leukocytes playing a role in metabolic derangements." (PMID 35050903, 2022). "In contrast, only IPI-549 delayed/prevented cachexia, and only IPI-549 improved Ndufs4(KO) performance on a rotarod assay, which assesses neurologic function and overall health." (PMID 35050903, 2022).
esophageal squamous cell carcinoma (1 paper, 2022). Esophageal squamous cell carcinoma (ESCC) is a type of esophageal carcinoma (EC) that can affect any part of the esophagus, but is usually located in the upper or middle third. "Levodopa was shown to inhibit the proliferation of esophageal squamous cell carcinoma (ESCC) via down-regulating the levels of oxidative phosphorylation proteins which includes MT-CO3, SDHD and NDUFS4." (PMID 35392560, 2022).
experimental autoimmune encephalomyelitis (1 paper, 2023). An autoimmune demyelinating disease of the central nervous system that is produced experimentally in animals by the injection of homogenized brain or spinal cord in Freund's adjuvant. "Lastly, it is notable that 3 mouse models of brain disease that are alleviated with hypoxia—Ndufs4 KO, experimental autoimmune encephalomyelitis, and Ercc1 Δ/-—demonstrate severe neuroinflammation as a major feature of their pathology." (PMID 37220109, 2023).
gastric cancer (1 paper, 2025). A primary or metastatic malignant neoplasm involving the stomach. "In cancer, NDUFS4 expression has been linked to tumor progression: in gastric cancer, it is significantly overexpressed compared to normal tissue, with elevated levels correlating with advanced stage and poor survival." (PMID 41157129, 2025). "Experimental silencing of NDUFS4 reduced proliferation and invasion of gastric cancer cells, while in xenograft models tumor growth was markedly suppressed." (PMID 41157129, 2025).
gastric tumour (1 paper, 2019). "Moreover, JS‐K administration suppressed Ndufs4 and COX2 expression in gastric tumour tissues." (PMID 30672108, 2019).
glioblastoma (1 paper, 2023). The most malignant astrocytic tumor (WHO grade IV). "This is consistent with a previous report that showed that GO attenuates the expression of genes associated with the oxidative phosphorylation complexes, such as NDUFA1, NDUFB3, and NDUFS4 in glioblastoma U87 cell line." (PMID 36839713, 2023).
Infertility (1 paper, 2025). "By linking specific splice variants (like the Ndufs4) to known aging phenotypes (mitochondrial ROS and infertility), we provide a proof-of-concept that isoform changes could be more than molecular noise, but may be pivotal pieces of the aging puzzle." (PMID 40475576, 2025).
iron deficiency (1 paper, 2023). "Iron deficiency in Ndufs4−/− mice prevented the altered expression of these genes, consistent with reduced cellular iron." (PMID 36799301, 2023).
ischemia reperfusion injury (1 paper, 2023). Adverse functional, metabolic, or structural changes in ischemic tissues resulting from the restoration of blood flow to the tissue (reperfusion), including swelling; hemorrhage; necrosis; and damage from free radicals. "A recent study suggested that heart-specific knockout of Ndufs4 ameliorates ischemia-reperfusion injury, and another research even showed that low abundance of NDUFV2 and NDUFS4 subunits predicts mammalian longevity." (PMID 36741296, 2023).
larynx squamous cell carcinoma (1 paper, 2022). "We observed a gene cluster, containing three genes (UQCRQ, NDUFA2, and NDUFS4) with different expression in various tumor stages of larynx squamous cell carcinoma, in modules related to tumor stage." (PMID 35715770, 2022).
lymphopenia (1 paper, 2025). Reduction in the number of lymphocytes. "Collectively, these data validate that Ndufs4(-/-) mice are characterized by intact thymic development and T-cell lymphopenia, which probably resulted from impaired homeostatic expansion." (PMID 41573538, 2025). "In vivo, Ndufs4(-/-) mice show T-cell lymphopenia and impaired humoral and cytotoxic immunity." (PMID 41573538, 2025).
mental disorder (1 paper, 2017). A disease that has its basis in the disruption of mental process. "Furthermore, the Ndufs4 cKO mice may be a useful model to study the role of mitochondrial deficiencies in mental disorders." (PMID 28327638, 2017).
osteosclerosis (1 paper, 2024). Abnormally high bone density. "In vivo knockdown (KD) of NDUFS4 has been shown to effectively impede osteoclast differentiation, ultimately resulting in osteosclerosis." (PMID 37815897, 2024). "Additionally, the construction of mice with global NDUFS4 deletion resulted in systemic inflammation and osteosclerosis." (PMID 37815897, 2024).